INS (insulin)
Diseases named in the same sentence as INS in open-access papers (continued):
Sharing a sentence is not in itself a finding about the gene and the disease.
Hyperglycemia (continued). "Reduced insulin action can be compensated by increased insulin secretion, but when insulin production capacity is jeopardized, chronic hyperglycemia will develop." (PMID 36093068, 2022). "In both T1D and T2D, reduced and/or inadequately β-cell mass leads to insufficient insulin secretion and hyperglycemia." (PMID 35832432, 2022). "In these cases, generalised alterations of subcutaneous fat tissue or the presence of hypertriglyceridaemia and hyperglycaemia secondary to a sharp increase in insulin resistance (with elevated C-peptide values) are the most common features." (PMID 36387939, 2022). "It ameliorates hyperglycemia and insulin sensitivity in diabetic rats, potentially by modulating the expression of phosphoenolpyruvate carboxykinase, GLUT4, and AKT1 and AKT3 and inhibiting DNA glycation." (PMID 36632095, 2022). "Impaired β-cell function leads to insufficient insulin production, impaired glucose-stimulated insulin secretion, fasting hyperglycemia and development of T2D." (PMID 35669072, 2022). "In T2D, chronic hyperglycemia exerts toxic effect on beta cells (glucotoxicity) and leads to beta cell dysfunction, impaired insulin secretion, and beta cell apoptosis partly by inducing inflammatory processes." (PMID 35629988, 2022). "The reported hyperglycemia following the use of xylazine is probably due to a reduction in insulin release from the β-cells in the pancreas and/or an increase in glucagon release from the α-cells." (PMID 35203217, 2022). "Conversely, acute hyperglycaemia induced by glucose infusion reduced pancreatic sympathetic activity and increased basal and glucose- stimulated insulin release in vivo." (PMID 36327900, 2022). "Our findings demonstrated that the continuous, combined consumption of GTC and CCA for three weeks suppressed hyperglycemia and insulin after consuming a high-fat test meal containing 75 g of glucose and improved insulin sensitivity in healthy males." (PMID 36501092, 2022). "Acupuncture is effective in the management of various metabolic disorders such as hyperglycemia and overweight by alteration of the sympathetic nervous system and insulin signal defects." (PMID 34757591, 2022). "In T1D, autophagic activity was enhanced and more protective than expected because of hyperglycemia and low insulin; in contrast, in T2D, hyperinsulinemia suppressed autophagy induction." (PMID 36299884, 2022). "One well- known adverse effects of glucocorticoids is hyperglycemia, and a safe way for its management in hospitalized patients is administration of insulin." (PMID 35109925, 2022). "Previous studies have shown that absence of islet autoantibodies (GAD insulinoma antigen-2, zinc transporter 8, and insulin autoantibodies), modest hyperglycemia and higher urinary c-peptide creatinine ratio, should result in genetic testing for MODY." (PMID 35346144, 2022). "It has been shown that defects in the machinery of glucose-sensing resulted in insulin secretion impairment and severe hyperglycemia." (PMID 35336762, 2022). "It is characterized by chronic hyperglycemia and an inadequate response to circulatory insulin by peripheral tissues, which results in insulin resistance." (PMID 35502173, 2022). "on P2Y1-/- mice shows that these mice develop hyperglycemia as well as a tendency towards glucose intolerance and increased insulin secretion compared to WT mice." (PMID 37065173, 2022). "The typical symptoms of STZ-induced type 1 diabetic rats included polydipsia, polyphagia, polyuria, emaciation, hyperglycemia, and low insulin levels." (PMID 36237833, 2022). "This was linked to 1.4 and 1.7 increases in insulin levels in groups II and III, respectively, as well as hyperglycemia." (PMID 35996069, 2022). "Except the prolonged half-life, GLP-1 RAs share common mechanisms of action with the endogenous GLP-1: augmentation of hyperglycemia-induced insulin secretion, suppression of glucagon secretion at hyper- or euglycemia, and restoring the function of beta-cells." (PMID 35933633, 2022).
Hyperglycemia (continued). "Neonatal diabetes mellitus (NDM) is a rare (1:90,000 newborns) but potentially devastating metabolic disorder characterized by hyperglycemia combined with low levels of insulin." (PMID 35518939, 2022). "It is characterised by dysregulation of carbohydrate, lipid, and protein metabolism due to impaired insulin secretion, increased insulin resistance, or a combination of both, resulting in hyperglycaemia and chronic inflammation." (PMID 36147626, 2022). "Hyperglycemia-induced insulin secretion through the central pathway increased progesterone and neuropathy development." (PMID 35743808, 2022). "Chronic hyperglycemia (glucose toxicity) typically negatively affects beta-cell function, leading to poor insulin secretion, a state commonly referred to as beta-cell exhaustion or dysfunction." (PMID 35462815, 2022). "In normoxia hyperglycemia, it was observed a decrease of insulin-dependent glucose uptake and a further increase of lactate." (PMID 35328751, 2022). "Herein, maternal BMI and pregnancy hyperglycaemia seem to be important factors modulating the levels of HM insulin in GDM mothers." (PMID 36079876, 2022). "It is characterized by chronic hyperglycemia with carbohydrate, protein, and lipid metabolic disturbances due to defects in insulin action and/or insulin secretion." (PMID 35330135, 2022). "This coupled with the driving force of hyperglycaemia and disordered insulin production/function, altering platelet reactivity and the inflammatory profile, also contributes to mitochondrial dysfunction." (PMID 35563363, 2022). "Type 1 diabetes mellitus is an autoimmune disorder in which insulin-secreting pancreatic β-cells are destroyed, leading to uncontrolled hyperglycemia and hypoglycemic event, and devastating multiple complications." (PMID 35304548, 2022). "We venture to suggest that fetal beta cells start secreting insulin around the 10 -11th week of pregnancy, and in patients with HIP, once fetal beta cells start secreting insulin, fetal hyperinsulinemia persists with maternal hyperglycemia." (PMID 36540507, 2022). "Exercise sessions, depending on their type and duration, can induce hypo- or hyperglycemia in the early morning before taking breakfast, under intensive insulin therapy with a basal insulin." (PMID 36231598, 2022). "T2DM is a systemic, noncommunicable disease with multiple metabolic disorders, characterized by defects in insulin secretion and/or insulin action leading to hyperglycemia." (PMID 35620114, 2022). "In the present study, we verified the high prevalence of high HOMA-IR (24.7%; 95% CI; 22.8, 26.7) and insulin (12.2%; 95% CI; 11.1, 13.5), despite having a low prevalence of hyperglycemia (4.6%; 95% CI; 3.8, 5.4)." (PMID 36078265, 2022). "The correlation between impaired insulin signaling and CABs assumes high relevance in light of the association of T2D with an increased risk of cancer; our results, therefore, reinforce the hypothesis that one of the mechanisms by which hyperglycemia impacts on cancer is DNA damage." (PMID 35678366, 2022). "The direct damage of insulin-producing β-cells makes hyperglycemia a main metabolic pathology of T1DM." (PMID 35255986, 2022). "Our results demonstrate that hyperglycemia-induced nitration and the low phosphorylation of tyrosine residues in IRβ are difficult to resolve with insulin treatment for a period equal to the duration of hyperglycemia." (PMID 36552776, 2022). "Despite decades of optimization of basal-bolus insulin therapy, handling of post-prandial hyperglycemia with insulin injections remains an unmet need." (PMID 35103951, 2022). "Hyperglycemia occurs secondarily to the physiological response to stress hormones released during acute illness and also to metabolic dysregulations that impair insulin signaling." (PMID 36422255, 2022). "It results in apoptotic cell death via p38 MAPK, JNK, and NF-kB signaling, reducing insulin secretion and provoking hyperglycemia." (PMID 35821802, 2022).
Hyperglycemia (continued). "In T2DM, ER stress-induced dysfunction of pancreatic beta cells decreases insulin production and its bioactivity leading to hyperglycemia." (PMID 35628864, 2022). "The latest findings reveal that pancreatic β-cells of HMGCR knockout mice are accompanied by severe hyperglycemia due to compromised insulin secretion and impaired pancreatic β-cell proliferation." (PMID 35571202, 2022). "Patients are randomly allocated to tight glucose control to target normal fasting glucose concentrations with insulin versus tolerating hyperglycemia up to a predefined level." (PMID 36123593, 2022). "Alloxan-induced hyperglycemia and decreased insulin concentrations were reversed significantly by BV." (PMID 36341058, 2022). "On the contrary, daily average glucose levels in co-cultures maintained under normoglycemia were within the range of 5.0–5.5 mM postulated to lead to a decrease in β-cell volume and the resulting decay in insulin secretion compared to hyperglycemia." (PMID 36260620, 2022). "The carbohydrate type and content of a meal are the main determinants of postprandial hyperglycemia and insulin response." (PMID 35215472, 2022). "Type 2 diabetes, a metabolic complication represented by hyperglycemia, is originated by insufficiency in production or action of insulin." (PMID 35056159, 2022). "To investigate behavioral and physiologic changes associated with hyperglycemia and glycemic control, we utilized an STZ-induced hyperglycemia mouse model and insulin-pellet-implantation regime." (PMID 36552776, 2022). "This transcriptional coactivator stimulates gluconeogenesis in the liver, favoring hyperglycemia, whereas it improves insulin sensitivity in skeletal muscle." (PMID 35428325, 2022). "The surgical stress also has a deleterious effect on pancreatic β-cells, causing a metabolic disorder that releases catabolic hormones and reduces insulin secretion, resulting in hyperglycemia." (PMID 35315984, 2022). "Other major complications included respiratory failure in seven (7%), hyperglycaemia which required insulin therapy at some stage in six (6%), circulatory collapse in four (4%), renal failure in two (2%), and gastrointestinal bleeding in two (2%)." (PMID 36053577, 2022). "In later stages, with a gradual decline in β-cell function, insulin levels are insufficient to meet increased insulin requirements, which produce hyperglycemia." (PMID 35745279, 2022). "This can gradually fatigue the pancreas, resulting in the body producing less and less insulin, further raising blood sugar levels (hyperglycaemia)." (PMID 35875742, 2022). "COVID‐19 virus has the ability to bind to the ACE2 receptor in the lungs and pancreas, and by inactivating it, it disrupts insulin secretion and hyperglycemia." (PMID 36483858, 2022). "Associated with T1DM and associated immune-mediated reduction of β-cell mass is a reduction in islet insulin secretion capacity, which will lead to additional hyperglycaemia and dyslipidaemia in these patients." (PMID 35052612, 2022). "- Anti-hyperglycemia, insulin sensitizer (↓blood glucose, ↓plasma insulin, ↓HOMA-IR index, ↓blood glucose and insulin in GTT; ↓plasma TG and NEFA) in HFD-diabetic mice (100 mg/kg bw, p.o., 27 days)." (PMID 35769384, 2022). "Similar results have proved that insulin group and hyperglycemia have more enhanced systemic inflammation and higher inflammatory markers including D-dimer, C-reactive protein, TNF-a and other interleukins." (PMID 35725489, 2022). "This reduced beta cell mass loses the ability to maintain insulin oscillation, and a reduction in glucose-stimulated insulin secretion leads to hyperglycemia." (PMID 35163806, 2022). "Although both HFL and HFMP fed groups were protected from increased adiposity, only HFL feeding had beneficial effects on insulin sensitivity and hyperglycemia/insulinemia." (PMID 35418570, 2022).
Hyperglycemia (continued). "During hyperglycemia, elevated levels of H2S can open the KATP channels in the islets cell membrane, which can cause high hyperpolarization and lower insulin secretion." (PMID 35743160, 2022). "Second, only HbA1c testing was ascertained for glycemic assessment owing to its convenience and robustness as a marker of long-term dysglycemia, less affected by stress-induced hyperglycemia and insulin resistance owing to an acute cardiac event." (PMID 36051328, 2022). "In patients with CFRD without fasting hyperglycemia it is possible to use an insulin scheme that includes only meal covers; if fasting hyperglycemia is present, the bolus scheme with the integration of basal insulin in the evening should be implemented." (PMID 35887806, 2022). "The increase of circulating catecholamines inhibits the insulin secretion with consequent hyperglycemia." (PMID 35267894, 2022). "In T2D, hyperglycemia is generally viewed to be a consequence of peripheral tissue of insulin resistance and insufficient insulin secretion, though T2D is a heterogenous disorder." (PMID 35457285, 2022). "Rats made diabetic by STZ induction showed severe hyperglycemia related to a probable decrease in endogenous insulin secretion and release." (PMID 36559668, 2022). "Given that insulin exerts anabolic effects for muscle cells, insufficiency of insulin action and prolonged hyperglycemia result in muscle wasting, altered metabolic capacity, and reductions in muscle function." (PMID 35629342, 2022). "At present, insulin is the first-line medication for the treatment of hyperglycemia in women with DIP." (PMID 35585514, 2022). "The results from this study indicate that impaired insulin secretion is linked with hypokalemia in 17OHD patients with NGT, while hyperglycaemia is associated with high progesterone concentration after hypokalaemia was rectified." (PMID 35937831, 2022). "It has been demonstrated that the relationship between hyperglycemia and COVID-19 is a complex and bidirectional interaction: hormone dysregulations with insulin resistance and the intense cytokine storm in COVID-19 induce hyperglycemia." (PMID 35949446, 2022). "Glyburide, an insulin secretagogue leads to increased maternal insulin levels and thereby reduces maternal hyperglycaemia." (PMID 35258482, 2022). "Normal pancreatic β cells can produce as many as 1 million insulin molecules per minute and produce a 50-fold insulin secretory response to hyperglycemia." (PMID 36275658, 2022). "Dapagliflozin (DAPA), sodium-glucose cotransporter 2 (SGLT2) inhibitor, is an insulin-independent antidiabetic drug used to control hyperglycaemia by promoting glucose excretion from the kidney." (PMID 36326417, 2022). "Fasting hyperglycemia, an established hallmark of DM2, is caused by excessive production of glucose by the liver, resulting in the inability of insulin to suppress endogenous glucose production." (PMID 35409318, 2022). "The patient was treated with carbimazole and propranolol for Graves’ thyrotoxicosis and basal bolus insulin regimen (actrapid and protaphane) for hyperglycemia." (PMID 35382047, 2022). "MSCs have been shown to resolve hyperglycemia in a T1D animal model, as they enhance insulin secretion and pancreatic regeneration." (PMID 35805883, 2022). "They should also understand the physiopathology of hyperglycemia-induced insulin secretion connected between energy homeostasis and the central role of reproduction." (PMID 35743808, 2022). "The demand for increased insulin secretion leads to islet beta cell damage and eventual inadequacy of insulin secretion with resultant hyperglycemia." (PMID 36145186, 2022). "For example, apigenin controls hyperglycemia by raising the blood insulin levels, while rutin increases glucose uptake by peripheral tissues and improves insulin resistance." (PMID 35956793, 2022).
Hyperglycemia (continued). "For those with A1c > 7% and symptomatic hyperglycemia, it is recommended to start or increase the dose of insulin at least one day before discharge to check both the effectiveness and safety of the new strategy." (PMID 35246230, 2022). "Defects in insulin synthesis or secretion, or in both, are key features of DM, eventually leading to hyperglycemia." (PMID 35807304, 2022). "In contrast, ZDF rats become insulin resistant at 6 to 7 wk of age and have elevated concentrations of insulin, which progresses to a robust hyperglycemia by 10–14 wk of age." (PMID 35657616, 2022). "This activity should be inhibited when the liver becomes insulin resistant, but actually the liver lipid synthesis is increased, leading to hyperglycemia and hypertriglyceridemia." (PMID 36430435, 2022). "Muscle uses glucose as a main energy source and any dysfunction in glucose uptake, such as occurring in insulin-resistance, will not only compromise muscle function but also has systemic effects (e.g., hyperglycemia)." (PMID 35615361, 2022). "It is characterized by elevated blood glucose levels or hyperglycaemia due to abnormalities in either insulin secretion or/and insulin action." (PMID 36678541, 2022). "The basal–bolus insulin therapy regimen remains a useful treatment for many inpatients, especially those with symptomatic hyperglycemia, poor glycemic control prior to admission, and those who fail to maintain glucose control with basal insulin, plus DPP4-i." (PMID 35628938, 2022). "These defects disrupt insulin action in maintaining glucose levels, resulting in maternal hyperglycaemia." (PMID 36606162, 2022). "Over time, hyperglycemia-induced cellular oxidative stress and inflammation impair insulin secretion and β-cell function." (PMID 35326230, 2022). "A previous study revealed that differentiated insulin-producing cells from hUCMSCs resulted in alleviation of hyperglycemia (T1DM) in NOD mice." (PMID 36514009, 2022). "BBR was effective in reducing FBG only in the subgroup of FBG ≥100 which can be because of the induction of higher insulin secretion in hyperglycemia by BBR, as explained by a previous study." (PMID 36313096, 2022). "More specifically, three Class I studies reported wound infection, hyperglycemia requiring insulin administration, and GI hemorrhage as statistically significant side effects." (PMID 36685598, 2022). "In the pre-transition period, hyperglycemia remains comparatively stable, but the concentration of plasma insulin decreases." (PMID 36141135, 2022). "DM is a glucose metabolism disorder characterized by chronic hyperglycemia resulting from a deficit of insulin production and/or action." (PMID 35562979, 2022). "Changes in insulin sensitivity are probably secondary to inflammation although molecules other than cytokines in the serum can also reduce insulin signaling including FFAs, lipotoxicity, hyperglycemia, and hyperinsulinemia." (PMID 36504710, 2022). "In particular, hyperglycemia is intrinsically linked to the inhibition of PI3K p110α, a key mediator of insulin signaling." (PMID 35566091, 2022). "The administration of MEP effectively regulated hyperglycemia and hyperlipidemia and improved insulin sensitivity." (PMID 36276816, 2022). "These cells can mimic the function of human islets in vitro and in vivo and secrete human insulin into the serum of mice shortly after transplantation in a glucose-regulated manner, ameliorating hyperglycemia in diabetic mice." (PMID 36743933, 2022). "Practically, reducing insulin demand and lowering hyperglycemia and hyperlipidemia, known as the therapy of ‘resting’ β-cells, have been shown to be effective means of restoring insulin secretion function." (PMID 35929791, 2022). "The use of a stepwise algorithm to treat hyperglycemia with lowering glucose intake or treatment with insulin is recommended." (PMID 35565787, 2022).